FOXP3 (forkhead box P3)
Diseases named in the same sentence as FOXP3 in open-access papers (continued):
Sharing a sentence is not in itself a finding about the gene and the disease.
nephritis (10 papers, 2013 to 2024). Inflammation of renal tissue. "Studies of mouse models of nephritis have suggested that when an inhibitory anti-Tim-1 antibody (RMT1-10) is administered to mice with nephritis, Foxp3+ T cells accumulate in the mice, and the expression of the IL-10 mRNA increases." (PMID 34603337, 2021). "Treatment with Baicalin-induced Foxp3+ regulatory T cells for 4 weeks also relieved kidney inflammation and decreased renal scores when compared to the treatment with vehicle-induced Foxp3+ regulatory T cells." (PMID 30760702, 2019). "In contrast, depletion of Foxp3+ Tregs induced by diphtheria toxin aggravates T cell-mediated nephrotoxicity and nephritis in Foxp3-diphtheria toxin receptor transgenic mice." (PMID 28469165, 2017). "Histologic evaluation of organs revealed that Foxp3-GS mice exhibited severe tissue inflammation with immune cell infiltration of the lungs, small intestine and colon, nephritis with immunoglobulin G (IgG) deposition, as well as the presence of antinuclear antibodies (ANAs) in the sera." (PMID 38427731, 2024). "Intravenous injection of Baicalin-induced Foxp3+ regulatory T cells could relieve nephritis, inhibit Tfh cell differentiation and IL-21 production." (PMID 30760702, 2019). "In the group with inactive nephritis, significantly higher percentage and absolute count of CD4+CD25+Foxp3+ regulatory cells have been observed compared to the group with active LN." (PMID 27156107, 2016). "Renal cortical IFN-γ, IL-4, IL-10, IL-17, and Foxp3 gene expressions were significantly higher in the WKY-HBSS rats than in WKY rats without nephritis, as assessed by real-time RT-PCR." (PMID 23826305, 2013).
prostate tumor (10 papers, 2012 to 2021). "FOXP3, a well-known breast and prostate tumor suppressor from the X chromosome, is a novel transcriptional repressor for several oncogenes." (PMID 34768829, 2021). "TRAMP-C2 prostate tumors from the 4 different treatment groups of mice were assessed using RT-PCR for the presence of mRNA of cytokines and other antitumor immune response markers, as well as for the T-regulatory cell marker, FoxP3." (PMID 22159900, 2012). "Abundant immune cells have been detected in prostate tumor tissues by immunohistochemistry using different markers (CD3+, CD8+, CD20+, CD56+, CD68+ and Foxp3+)." (PMID 27368058, 2016).
Sjögren syndrome (10 papers, 2013 to 2024). "Topical administration of a CD47-binding TSP-1 peptide during the development of an ocular inflammation has been described to attenuate clinical symptoms of Sjögren syndrome-associated dry eye and augment FoxP3 expression." (PMID 31214201, 2019). "Future studies are needed to evaluate if the increased DS induced inflammation in the mouse model and the inverse correlation between stool microbiome diversity in Sjögren syndrome is related to decreased generation of Foxp3+Tregs generation." (PMID 27087247, 2016). "The aims of this study were to explore intestinal microbial composition and functionality in primary Sjögren’s syndrome (pSS) and to relate these findings to inflammation, permeability and the transcription factor Forkhead box protein P3 (FOXP3) gene expression in peripheral blood." (PMID 33228011, 2020). "Indeed, there is evidence that the colonization of germ-free mice with the GM derived from Sjögren’s syndrome patients decreases the abundance of CD4+ forkhead box P3 (FOXP3)+ Treg cells in cervical lymph nodes and promotes corneal barrier damage following dry eye induction." (PMID 37686143, 2023).
T-cell lymphoma (10 papers, 2011 to 2026). "Karpas-299, a human T cell lymphoma cell line that expresses Foxp3 and shows characteristics typical of Tregs, was used." (PMID 27284967, 2016). "First, the frequency of Foxp3 positive cells in T-cell lymphomas was similar in HBZ-Tg mice and in ATL." (PMID 21347344, 2011). "In this study, we show that transgenic expression of HBZ increases Foxp3+ Treg cells and effector/memory T cells, leading to development of T-cell lymphomas and systemic inflammatory diseases." (PMID 21347344, 2011).
thymoma (10 papers, 2018 to 2024). A neoplasm arising from the epithelial cells of the thymus. "In a wide cohort of 100 thymomas and 69 TCs tissue expression of PD-L1, IDO and FOXP3 was analyzed and higher PD-L1 staining was detected in 36% of cases of both thymomas and TCs." (PMID 36046087, 2021). "They identify FoxP3 as one of the targets of miR-125a-5p and FoxP3 expression is known to be altered in thymoma patients." (PMID 32587589, 2020). "In TAMG, the abnormally increased miR-125a could inhibit the expression of Foxp3, and thus reduce the Treg cell in thymoma." (PMID 39318549, 2024). "Then in 2010, observation was followed which unveiled that the mutation of epithelial expression Aire gene in B2 thymoma induces the absence of myoid cells, thus resulting in the loss of Foxp3+ T cells." (PMID 29773681, 2018). "In typical thymomas and thymic SCC, type B thymoma and thymic SCC presented a larger number of FOXP3 (+) T cells than did type A or AB thymoma, and the prognosis of type B thymoma and thymic SCC was worse than that of type A or AB thymoma in previous studies." (PMID 33819365, 2021). "In the micro-environment, a large series of 100 thymomas and 69 thymic carcinomas reported high expression of PD-L1, IDO and FOXP3 Tregs in 36%, 13% and 16% of cases of thymoma, respectively." (PMID 35757304, 2019). "And the lost Foxp3+ T cells perhaps related with the impairing negative selection in thymoma." (PMID 29773681, 2018).
thyroiditis (10 papers, 2014 to 2026). Inflammation of the thyroid gland. "Their absence in MNG tissues suggests that FoxP3 expression could serve as a distinguishing factor between benign and malignant thyroid conditions." (PMID 41189243, 2025). "CD4+/CD25+/Foxp3+ regulatory T-cells and Foxp3 gene expression were reduced in mice with iodine-induced thyroiditis, and the number of regulatory T-cells was negatively related to the severity of thyroiditis." (PMID 25050783, 2014).
acute coronary syndrome (9 papers, 2014 to 2023). Signs and symptoms related to acute ischemia of the myocardium secondary to coronary artery disease. "A large number of clinical studies showed that peripheral blood Treg cell subsets in patients with acute coronary syndrome decreased significantly compared with patients with stable angina and associated with reduction in mRNA expression of Foxp3 and TGF-β1 in plasma." (PMID 29137256, 2017). "Consistent with this purported function, it has been previously shown that acute coronary syndrome (ACS), a chronic inflammatory disease, is associated with a reduction in the number and function of circulating “classical” CD4+CD25+FOXP3+ Tregs." (PMID 24558424, 2014). "Patients with the acute coronary syndrome also displayed decreased mRNA levels of galectin-9, TIM-3, and forkhead box P3 (Foxp3) in peripheral blood mononuclear cells." (PMID 36873388, 2023). "In PBMCs of patients with acute coronary syndrome, in-vitro simvastatin 10 μM was able to increase the percentage of CD4 + CD25 + FoxP3+ regulatory T cells to total CD4+ cells." (PMID 26822994, 2016).
B cell lymphoma (9 papers, 2010 to 2021). "Another example is that Tregs were associated with good outcome in B-cell lymphoma when they were identified by Foxp3 alone, but Tregs were associated with poor patient outcome when they were identified by both CTLA-4 and Foxp3." (PMID 33086518, 2020). "In a study conducted by El-Sayed and colleagues, it was shown that mRNA transcripts as well as percentages of FoxP3 were significantly increased in B-cell NHL patients before receiving CHOP, when compared to healthy controls." (PMID 30473875, 2018). "We found a significantly higher percentage of CD4+CD25+FoxP3+CD127lo Treg presented in PB as well as BM samples from B-cell NHL compared with PB samples from HVs." (PMID 22174855, 2011). "By showing that Foxp3 induces miR-155 our study hints at a new role for Foxp3 in B cell lymphoma development." (PMID 20209161, 2010). "Investigators have found that co-injection of MSCs with neoplastic (A20) B cells promotes B cell lymphoma growth in the lacrimal glands of immunocompetent mice and were associated with marked increased in CD4+ forkhead box P3 (FoxP3) + T cells and myeloid-derived suppressor cells." (PMID 30101129, 2018). "To investigate a possible role of CD4+CD25+FoxP3+CD127lo Treg in the immune system in B-cell NHL, both peripheral tolerance and the tumor microenvironment, we measured the frequencies of CD4+CD25+FoxP3+CD127lo Treg in PB, BM and involved lymphatic tissues from patients with B-cell NHL." (PMID 22174855, 2011). "The consequence of these overrepresented CD4+CD25+FoxP3+CD127lo Treg in B-cell NHL remains unknown." (PMID 22174855, 2011). "Here we demonstrated that CD4+CD25+FoxP3+CD127lo Treg were markedly increased and their phenotypes were different in peripheral blood (PB) as well as bone marrow (BM) from newly diagnosed patients with B-cell NHL compared with those from healthy volunteers (HVs)." (PMID 22174855, 2011). "In summary, we have showed an increased frequency and suppressive activity of CD4+CD25+FoxP3+CD127lo Treg in PB, BM, and involved lymphatic tissues from patients with B-cell NHL, which might play a critical role in suppressing the host immune responses to tumor." (PMID 22174855, 2011). "In murine model of lacrimal gland B-cell lymphomas, those lymphoma cells that were coinjected with MSCs were found to have increased CD4+ Foxp3+ regulatory T cells as well as CD11b+ Ly6C+Ly6G– MDSCs." (PMID 30101129, 2018). "Increased in Foxp3 mRNA and protein expression were observed in both cultured CD19+ primary B cells isolated from splenocytes of wild type mice (WT), and in a mouse B cell lymphoma line (A20), after LPS or IgM mAb stimulation." (PMID 27350539, 2016). "FOXP3, MHC class II, age at presentation and rescue therapy are independent prognostic factors in canine B cell lymphoma." (PMID 25119018, 2014). "Helios+ FoxP3+ T cells in A20 B cell lymphoma tumors largely lacked CCR7 expression." (PMID 22292042, 2012).
coronary artery disease (9 papers, 2013 to 2022). "Expression of PD-L1 on CD4+CD25+FOXP3+ regulatory T cells in peripheral blood is negatively correlated with the severity of coronary heart disease." (PMID 39050559, 2022). "In patients with coronary artery disease, increased expression of full-length FOXP3 is seen and induced by T cell receptor (TCR) stimulation." (PMID 33176790, 2020). "Our results show a negative correlation between plasma levels of IL-21 and Foxp3 and a positive correlation between plasma ApoAI and Treg and in human samples obtained from patients with coronary artery disease, indicating that our findings in atherosclerotic mouse models have relevance in humans." (PMID 29545616, 2018).
lung disease (9 papers, 2010 to 2023). "Next, we evaluated the changes in levels of IL-10, a regulatory T cell (CD4 + FoxP3+ T-regs)-associated immunosuppressive cytokine, as T-reg dysfunction is implicated in chronic CF-lung disease pathogenesis." (PMID 29301535, 2018). "In the SR-triggered farmer's lung disease model, Foxp3+ CD4+ T cells are the majority of the IL-10-producing LAG3+CD49b+ T cell subset in the lungs, however, there are similar percentages of Foxp3− CD4+ and CD8+ T cells (16% each)." (PMID 30510554, 2018). "Pulmonary disease caused by RSV infection involves a complex interplay of inflammatory and anti-inflammatory immune responses, tightly regulated by Foxp3+ Treg cells." (PMID 23926350, 2013). "Major populations of regulatory T cells studied in the context of lung diseases are natural thymic-derived CD4+CD25+Foxp3+ Treg cells and peripherally antigen-induced CD4+ Treg cells, which comprise both Foxp3-positive and –negative populations." (PMID 21072213, 2010). "Therefore, the balance of Treg and Th17 cells can be regulated by adjusting the expression of cytokines such as IL-17A, IL-6, IL-23, IL-33 and Foxp3 to achieve the goal of treating lung diseases." (PMID 37795866, 2023). "After the resolution of lung viral load, activated macrophages that express the co-stimulatory molecule CD86 induce the expansion of forkhead box P3 (FOXP3+) regulatory T-cells (Tregs) to promote the recovery from pulmonary diseases via the suppression of neutrophil-driven cytokine release." (PMID 32962304, 2020). "Moreover, studying twin pairs longitudinally will enable a better understanding of the possible molecular linkage between lung disease and methylation of CpG sites in FOXP3 and IFNγ in Treg and Teff, respectively." (PMID 23226205, 2012).
Miscarriage (9 papers, 2015 to 2026). A pregnancy that ends at a stage in which the fetus is incapable of surviving on its own, defined as the spontaneous loss of a fetus before the 22th week of pregnancy. "Genetic susceptibility may be involved in the onset of recurrent miscarriage and play an important role in the occurrence and development of RM 30; such genes include FOXP3, IL‐10, and TNF‐α." (PMID 31454102, 2019). "The reduction of the population of circulating CD4+CD25+Foxp3+ regulatory T cells exhibit impaired immune regulatory mechanisms in pregnancy complicated by miscarriage." (PMID 25945787, 2015). "In our findings the percentage of circulating CD4+CD25+Foxp3+ T cells was significantly lower in miscarriage in comparison to normal pregnancies (p = 0.003)." (PMID 25945787, 2015). "In details, lnc‐HZ05 suppresses FOXP3‐mediated TGFβ2 mRNA transcription, promotes autophagy degradation of TGFβ2 protein, impairs TGFβ2/TGFβR2 protein interactions, and eventually induce unexplained miscarriage." (PMID 41168951, 2026). "However, the expression of PD-1/PD-L1 and Foxp3 was significantly decreased in the placenta and spleen in the AIT-related miscarriage group." (PMID 32351559, 2020).
nasopharyngeal carcinoma (9 papers, 2007 to 2024). A carcinoma arising from the nasopharyngeal epithelium. "The FOXP3 concentration from local primary nasopharyngeal cancer specimen was moderately associated with GTVp volume (ρ Spearman correlation coefficient of 0.6; p value = 0.002)." (PMID 35963999, 2022). "The LMP1 was also found to have positive association with FOXP3 concentration from local primary nasopharyngeal cancer specimen." (PMID 35963999, 2022). "A previous study indicated that TA increases FOXP3 expression to inhibit the progression of nasopharyngeal carcinoma." (PMID 39483046, 2024). "Previous studies have shown that TA can increase FOXP3 expression to inhibit nasopharyngeal carcinoma progression." (PMID 39483046, 2024). "The FOXP3 marker from local primary nasopharyngeal cancer specimen was also positively related to tumor progressions in primary site." (PMID 35963999, 2022). "Higher LMP1 concentration from local primary nasopharyngeal cancer specimen was related with higher FOXP3 concentration from local primary nasopharyngeal cancer specimen." (PMID 35963999, 2022). "In nasopharyngeal carcinomas, the density of Foxp3+ TILs was correlated to better overall survival and progression-free survival." (PMID 21437225, 2010). "An increase of CD4+CD25+Foxp3+ Tregs has been observed in the peripheral blood and in the tumor site of patients with nasopharyngeal carcinoma." (PMID 21437225, 2010). "Thus, all of these findings further supported the possibility of higher FOXP3 markers in larger primary nasopharyngeal cancer." (PMID 35963999, 2022). "Therefore, this study was aimed to elucidate the association with EBV oncoproteins (EBNA1 and LMP1), immune markers (CD4, CD8, and FOXP3) from nasopharyngeal cancer microenvironment with tumor progression." (PMID 35963999, 2022). "The nasopharyngeal cancer was also known to upregulate chemokines that could recruit T regulatory FOXP3 cells." (PMID 35963999, 2022). "The purpose of this study was to evaluate the expression and localization of CD8, FoxP3, PD-1, and PD-L1 in primary tumor tissues and their effects on prognosis of stage IV M0 locally advanced nasopharyngeal carcinoma (NPC) patients." (PMID 31138162, 2019). "Those samples with microscopically confirmed nasopharyngeal cancer were tested for EBNA1, LMP1, CD4, CD8, and FOXP3 concentration with ELISA, then verified with IHC." (PMID 35963999, 2022). "The positive LMP1 correlation found with local FOXP3 marker concentration from primary nasopharyngeal cancer specimen was perhaps due to indirect effect of both LMP1 and FOXP3 in promoting tumor progression, instead of the direct effect of LMP1 toward T regulatory cells." (PMID 35963999, 2022). "In nasopharyngeal carcinoma (NPC), miR-24-3p is profoundly upregulated in TDEs that can be delivered into T cells, where it then inhibits the percentage of CD4+ T cells and decreases the production of IFN-γ and IL-17 while provoking the augment of CD4+ Foxp3+ T cells (Tregs)." (PMID 35663957, 2022).
ovarian tumors (9 papers, 2014 to 2025). "In ovarian tumours, high FoxP3 T‐cells have been associated with a reduction in Th1 response and worse prognosis." (PMID 33481339, 2021). "For instance, mice expressing human MUC1, and exhibiting Pten deletion and an activating Kras mutation, spontaneously develop ovarian tumors highly infiltrated by FOXP3+ Treg and dysfunctional DC." (PMID 32630708, 2020). "We showed that TH1 cells accumulating in ovarian tumors are able to maintain an antitumor effector phenotype, despite a concomitant high infiltration by FOXP3+ Treg." (PMID 32630708, 2020). "In addition, we previously demonstrated that a major subset of CXCR3+T-bet+Helios+FOXP3+ Treg selectively accumulated in ovarian tumors, and suppressed the proliferation of IFN-γ production by effector T-cells." (PMID 32630708, 2020). "In clinical trials of combination therapy in ovarian tumors, the Pan-Bcl-2 inhibitor GX15-070 (Obatola) was found to significantly downregulate FoxP3, a Treg cell-specific marker." (PMID 40216744, 2025). "A TNFR2 antagonists could specifically inhibit CD4+Foxp3+ Tregs expansion in the tumor microenvironment, whereas it had little inhibitory effects on CD4+ Tregs in periphery or from healthy donors, and killed human ovarian tumor cells directly." (PMID 29623079, 2018).